OPTN (optineurin)
Diseases named in the same sentence as OPTN in open-access papers (continued):
Sharing a sentence is not in itself a finding about the gene and the disease.
cancer (continued). "Emerging evidence suggests that OPTN has a complex and context-dependent role in cancer biology as well." (PMID 41294799, 2025). "Although OPTN accelerates autophagy of cancer cells, we are unaware of studies into its role in mitophagy." (PMID 33600074, 2021). "In this review, we summarized the most important findings related with the pro-tumorigenic role of autophagy receptors p62/SQSTM1, NBR1, NDP52, and OPTN in cancer progression." (PMID 33634029, 2020). "For assessing the expression of OPTN in human cancers, publically available databases were explored." (PMID 31428460, 2019). "Our results hint to OPTN as a versatile factor in the progression of cancer in general and of PDAC in particular." (PMID 31428460, 2019). "Induction of optineurin gene expression by metastasis promoting protein S100A4 and the regulation of optineurin promoter by NF-κB provide a basis for exploring the role of optineurin in cancer development." (PMID 19340308, 2009). "Notably, PRKN exhibited the highest alteration frequency, affecting 34% of all cancer samples, followed by OPTN (21%), PINK1 (18%), SRC (15%), BECN1 (13%), MAP1LC3A (9%), and BNIP3L (5%)." (PMID 39859167, 2025). "Here, we conduct a comprehensive analysis of a mitophagy-related gene signature, composed of PRKN, PINK1, MAP1LC3A, SRC, BNIP3L, BECN1, and OPTN, across various cancer types, revealing significant differential expression patterns associated with molecular subtypes, stages, and patient outcomes." (PMID 39859167, 2025). "In another study, the downregulation of HACE1 and OPTN proteins was observed in various cancers." (PMID 39859167, 2025). "Studies have shown that the overexpression of RAB1A in cancer cells may promote autophagy progression by effecting with optic nerve protein (OPTN, an autophagy receptor)." (PMID 38436022, 2024). "Interestingly, several cytosolic autophagy receptors such as p62/SQSTM1, NBR1, NDP52 and OPTN have been reported to be overexpressed in several types of cancer playing regulatory roles in the last stage of carcinogenesis." (PMID 33634029, 2020). "Ferritin light chain was shown previously to be enriched in autophagosomal fractions from cancer cell lines as was calcium-binding and coiled-coil domain-containing protein 2, optineurin, autophagy-related protein 9A, all of which were also identified in this study." (PMID 26258666, 2015). "Similarly, the modulation of the activity of MAP1LC3A (LC3) and OPTN could influence autophagosome formation and selective degradation of mitochondria, thereby affecting cancer cell survival." (PMID 39859167, 2025). "Similarly, modulating the activity of SRC and OPTN might affect autophagosome formation and selective degradation of mitochondria, influencing cancer cell survival and drug resistance." (PMID 39859167, 2025). "Heterozygous deletions were prevalent in PRKN, BNIP3L, OPTN, and PINK1, particularly in cancers such as LUSC, ESCA, HNSC, and COAD." (PMID 39859167, 2025). "Last, we gathered the IC50s of a wide variety of drugs among different cancer cell lines through the GDSC and CTRP databases and assessed the relationship between the mRNA values of MAP1LC3A, OPTN, SRC, BNIP3L, BECN1, PINK1, and PRKN and drug sensitivity." (PMID 39859167, 2025). "The analysis of CNVs in PRKN, OPTN, PINK1, SRC, BNIP3L, BECN1, and MAP1LC3A across various cancer types revealed significant heterogeneity in the types and frequencies of CNVs." (PMID 39859167, 2025). "Immunohistochemical analysis revealed that OPTN was expressed in the cytoplasm of the cells of 141 resected HCC tissues and at higher levels in cancer versus adjacent tissues." (PMID 33600074, 2021). "Overall, these findings highlight the complex landscape of CNVs in PRKN, OPTN, PINK1, SRC, BECN1, BNIP3L, and MAP1LC3A across different cancer types, emphasizing the potential impact of these genetic alterations on cancer pathogenesis and the importance of considering CNVs in therapeutic strategies." (PMID 39859167, 2025).
cancer (continued). "Thus, we investigated the role of OPTN in PDAC, a cancer with almost identical incidence and mortality rates." (PMID 31428460, 2019). "We also show that activated OPTN has a potential activating effect on the activity of EMT (25%) and Apoptosis (16%) pathways, as well as a potential inhibitory effect on the activity of the Cell cycle (19%), DNA damage (16%) hormone AR (16%) and PI3K/AKT (12%) in pan-cancer." (PMID 39859167, 2025). "Knockdown of OPTN in PDAC cell lines leads to endoplasmic reticulum (ER) stress activation and apoptosis, accompanied by an increase in chaperone-mediated autophagy (CMA), suggesting that cancer cells rely on alternative autophagy pathways when macroautophagy is disrupted." (PMID 41294799, 2025). "Therefore, we conclude that OPTN contributes to cancer progression independent of p62‐mediated pathways." (PMID 33600074, 2021).
neurological diseases (8 papers, 2016 to 2025). "TBK1, OPTN, p97, and other factors involved in selective autophagy are mutated in a variety of neurological disorders such as ALS and FTD." (PMID 34585663, 2021). "The dysfunction of optineurin is associated with neurological diseases." (PMID 39996775, 2025). "Like the previous comparison, several of these transcripts, such as CELF5, DEPTOR, DLG2, OPTN and STX3, have been linked to brain functions and neurological disorders, supporting the fact that these hnRNP proteins can work in a network to regulate at least specific sets of targets." (PMID 36267332, 2022). "It is assumed that the development of these neurological diseases is due to impaired fusion of autophagosomes with lysosomes (inhibition of the NF-kB signaling pathway is enhanced), but the mutant TBK1, OPTN, and SQSTM1 genes also contribute to the pathogenesis." (PMID 39403278, 2024).
bacterial infection (5 papers, 2015 to 2022). "Collectively, these data demonstrate that OPTN limits bacterial infection in the intestine likely by mediating selective autophagy and pathogen clearance." (PMID 29692785, 2018). "Preliminary data in zebrafish suggests that OPTN is protective against bacterial infection, replicating the findings in mice." (PMID 26044960, 2015). "In this study, we show that OPTN plays an important role in the inflammatory response and in neutrophil recruitment, which are important in controlling bacterial infection in the bowel." (PMID 26044960, 2015). "Some studies suggest that up to 70% of the TBK1 activity is the result of its interaction with the adaptor protein OPTN, while other studies have reported that TBK1 regulates the autophagy receptors OPTN and p62 during bacterial infection by phosphorylating the UBAN domain on these proteins." (PMID 34800171, 2022).
autosomal dominant disease (1 paper, 2022). Autosomal dominant form of disease. "NTG caused by OPTN (E50K) mutation is an autosomal dominant disease." (PMID 35436991, 2022).
myopathy (1 paper, 2023). A disease of the muscle in which the muscle fibers do not function properly. "OPTN, encoding a protein involved in ubiquitin‐dependent autophagy, may also represent another MSP gene as OPTN mutations were reported as causative of ALS and risk factor for PDB, but not as causative of myopathy." (PMID 36861178, 2023).
OPTN also shares sentences with these, for which no sentence is quoted: gastric cancer (6 papers); dementia (4); Parkinsonism (3); Blindness (2); fatty liver disease (2); inclusion body myositis (2); Leber hereditary optic neuropathy (2); melanoma (2); motor neuron degeneration (2); osteosarcoma (2); Primary lateral sclerosis (2); prostate carcinoma (2); acute liver failure (1); acute myeloid leukemia (1); age (1); age-related macular degeneration (1); asthma (1); autosomal dominant optic atrophy (1); bone disorder (1); Brain atrophy (1); Charcot-Marie-Tooth disease type 4 (1); chronic obstructive pulmonary disease (1); cognitive deficits (1); corticobasal syndrome (1); deafness (1); distal hereditary motor neuropathies (1); Duchenne muscular dystrophy (1); esophageal carcinoma (1); familial amyotrophic lateral sclerosis (1); gastric tumor (1).
A further 33 diseases each share a sentence with OPTN in 1 paper.